MTOR (mechanistic target of rapamycin kinase)
Diseases named in the same sentence as MTOR in open-access papers (continued):
Sharing a sentence is not in itself a finding about the gene and the disease.
breast cancer (continued). "Inhibitors of proteins in the AKT/mTOR pathway, including everolimus, are currently being tested in the clinic as new therapeutic agents in breast cancer patients." (PMID 26771843, 2016). "Concomitant inhibition of MAPK and PI3K/mTOR signaling was shown to be synergistic in mouse models of breast cancer." (PMID 27374081, 2016). "There is emerging evidence that constitutive activation of PI3K/Akt/mTOR pathway plays a critical role in the survival and growth of breast cancer cells." (PMID 26565813, 2016). "Here, we identified Cav-1 is mechanosensitive to LSS exposure, and its activation-induced PI3K/Akt/mTOR signaling promotes motility, invadopodia formation and metastasis of breast carcinoma MDA-MB-231 cells." (PMID 26919102, 2016). "In the present study, we found that NHPI selectively inhibited the proliferation of human breast carcinoma BT-20 cells and human colon adenocarcinoma LoVo cells, concomitantly suppressing mTOR signaling pathway." (PMID 26940018, 2016). "Several dual PI3K/mTOR inhibitors are also currently being investigated in phase II studies in different types of tumors including HR+ advanced breast cancer." (PMID 26059247, 2015). "Akt/mTOR pathway involves in various pathological mechanisms of colorectal cancer, gastric cancer, liver cancer, breast cancer and uterine cancer etc.." (PMID 25884175, 2015). "Phenformin induced cell cycle change and apoptosis in breast cancer cells via the AMPK/mTOR/p70s6k and MAPK/ERK pathways." (PMID 26114294, 2015). "Activation of the Akt/mTOR pathway contributes to increased cell invasiveness in prostate cancer and breast cancer." (PMID 26502919, 2015). "PIK3CA has also been suggested as a predictive marker for effective mTOR inhibition in breast cancer, unfortunately, a recent report on endometrial cancer did not support this." (PMID 25962426, 2015). "Several phase II and III studies including an mTOR inhibitor have been completed in patients with advanced hormone receptor (HR)+ breast cancer, and so far three major randomized trials have reported consistent data in efficacy." (PMID 26059247, 2015). "Taken together, these data underscore the therapeutic potential of using Hhat inhibitors alone or in combination with PI3K/mTOR inhibitors or ER modulators to treat breast cancer and circumvent or delay resistance to current treatments." (PMID 25889650, 2015). "This has been investigated in PDX models of basal-like breast cancer using combined mTOR and AKT inhibitors." (PMID 25849559, 2015). "It was reported that the expression of STAT3 decreases in breast cancer cells transfected with lentivirus-based shRNAs targeting the mTOR gene." (PMID 25658305, 2015). "The phosphatidylinositol 3-kinase (PI3K)/AKT/mammalian target of rapamycin (mTOR) signalling network is frequently de-regulated in breast cancer and has been shown to mediate resistance to anti-HER2 agents." (PMID 26095475, 2015). "In human breast cancer xenografts we confirm that such differential sensitivity to therapy is primarily determined by the level of PI3K/Akt/mTOR in tumor cells." (PMID 26098779, 2015). "We report the acquisition of several deregulated miRNAs as a newly discovered alternative mechanism developed by the AI-resistant breast cancer cells to achieve constitutive activation of the AKT/mTOR pathway and to develop AI resistance." (PMID 25633049, 2015). "On the other hand, it was reported to be involved in the activation of the Akt/mTOR signaling pathway, downregulated ERalpha, and the reduction of the antitumor effect of tamoxifen in breast cancer in vitro." (PMID 26063961, 2015). "Similar results were observed for MCF7 breast cancer cells with a concentration-dependent increase of phosphorylated mTOR and p70S6K as well as total levels of mTOR." (PMID 25460505, 2015). "The EEF2 protein is inactivated by phosphorylation, and inactivation of EF2K is increased by mTOR activity in breast cancer cells." (PMID 25693800, 2015).
breast cancer (continued). "Mammalian target of rapamycin (mTOR) inhibitors have anti-tumor effects against renal cell carcinoma, pancreatic neuroendocrine cancer and breast cancer." (PMID 25884680, 2015). "Further studies will need to identify optimal biomarkers for selecting breast cancer patients most likely to benefit from concerted treatment with combination therapies of mTor and cSRC inhibitors." (PMID 26205886, 2015). "The combination of mTOR inhibitors with endocrine therapy in second-line treatment of oestrogen receptor (ER) positive breast cancer has been shown successful, and this treatment regimen is now clinically approved." (PMID 26698305, 2015). "Modified expression of these genes is known to be involved in breast cancer pathways and include mTOR signaling pathway, focal adhesion, VEGF signaling pathway, and ErbB signaling pathway." (PMID 26512648, 2015). "The PI3-kinase (PI3K)/mTOR pathway is aberrantly activated up to 60% of clinical breast cancers, facilitating tumor cell growth, survival, metabolism, and invasion." (PMID 26132202, 2015). "Activation of the phosphoinositide 3 kinase (PI3K)/Akt/mammalian target of rapamycin (mTOR) pathway is common in breast cancer." (PMID 26779371, 2015). "In conclusion, patients weighted importance on PFS, anemia, and pneumonitis, when they needed to choose an aromatase inhibitor plus mammalian target of rapamycin (mTOR) inhibitor for advanced breast cancer treatments after failure of standard treatments." (PMID 26558177, 2015). "It is also reported that mTOR inhibitors in combination with exemestane can improve progression-free survival in postmenopausal breast cancer patients." (PMID 26517687, 2015). "More than 50% of ER/PR-positive breast cancers contain alterations in at least one component of the PI3K/Akt/mTOR pathway, and these alterations drive cancer growth and also facilitate development of resistance to hormone prevention therapies." (PMID 26098779, 2015). "We also extended our studies to include breast cancer cells as mTOR is emerging as an important target for breast cancer treatment." (PMID 25460505, 2015). "mTOR pathway inhibitors, such as everolimus, should theoretically be of benefit in breast cancer as a result of the dysregulation of this pathway demonstrated by molecular studies, although initial results have been disappointing." (PMID 25627134, 2015). "Remarkably, araguspongine C treatment resulted in the suppression of PI3K/Akt/mTOR signaling cascade in breast cancer cells undergoing autophagy." (PMID 25580621, 2015). "Direct pharmacologic inhibition of the PI3K/AKT/mTOR signaling is, therefore, an attractive clinical strategy for breast cancer." (PMID 25932042, 2015). "Combination therapy has been proven to be effective in multiple cancer types, such as PI3K and MEK inhibition in KRAS or EGFR driven cancers and mTOR and aromatase inhibition in breast cancer." (PMID 26509262, 2015). "Many efforts have been performed in order to identify potential biomarkers of benefit from mTOR inhibition in patients with breast cancer." (PMID 26059247, 2015). "In fact, inhibition of PI3K/Akt/mTOR proved the activation of another important pathway dysregulated in breast cancer, the mitogen-activated protein kinase/extracellular signal-regulated kinase (MAPK/ERK) pathway." (PMID 26703550, 2015). "As a downstream effector of PI3K/mTOR, Akt is constitutively activated in many types of human tumors, including breast cancer." (PMID 25333576, 2015). "In breast cancer, the mTOR signalling pathway is commonly dysregulated and is implicated in resistance to current treatment." (PMID 25460505, 2015).
breast cancer (continued). "Another approach that is currently under study in patients with breast cancer brain metastases is targeting the phosphatidylinositol 3-kinase (PI3K)—mammalian target of rapamycin (mTOR) pathway." (PMID 26605131, 2015). "Although the PI3K/AKT/mTOR pathway is upregulated in a significant proportion of breast cancers, and has been shown a driver of malignancy, far from all patients benefit from treatment with mTOR pathway inhibitors." (PMID 26698305, 2015). "In this study, we focus on the downstream mTOR effectors S6K1, S6K2 and 4EBP1 that have been shown amplified and overexpressed in breast cancer and associated with an adverse prognosis, and also implicated as markers of outcome after endocrine treatment." (PMID 26698305, 2015). "The PI3K/Akt/mammalian target of rapamycin (mTOR) pathway can activate multiple oncogenic programs and is essential in regulating breast cancer cell growth." (PMID 26599012, 2015). "The mTOR pathway has emerged as an important target in breast cancer therapy, and the first generation of mTOR inhibitors has recently reached the clinic." (PMID 26698305, 2015). "Our study reports herein that not only tamoxifen-resistant breast cancer cells display altered glycolysis compared to tamoxifen-sensitive cells but also Akt/mTOR and AMPK signaling molecules are attributed to HIF-1α-regulated glucose metabolism in these cells." (PMID 26158266, 2015). "Phosphorylation of the mTOR target 4EBP1 has been identified as a marker of poor prognosis in several malignancies, including breast cancer." (PMID 26698305, 2015). "Given the importance of mTOR in breast cancer progression and treatment, an understanding of mTORC1 and mTORC2 in untransformed MECs is needed." (PMID 26132202, 2015). "The HORIZON trial was the first phase III randomised trial evaluating the use of an mTOR inhibitor in breast cancer." (PMID 26779371, 2015). "In this article, we review the literature on the relevance of the PAM pathway in breast cancer, the advances in targeting this pathway including potential biomarkers and targets, and provide a practical approach to the toxicity management of mTOR inhibition." (PMID 26779371, 2015). "In a broad series of breast cancer cell lines, sensitivity to the mTOR allosteric inhibitor everolimus, as measured by IC50 values, varied over a range of more than 570-fold." (PMID 26148118, 2015). "Pharmacologic and genetic evidences point to the PI3K/AKT/mTOR pathway as a key mediator of oncogenic signaling in breast cancer." (PMID 25932042, 2015). "We compared the efficiency of pan-PI3K, AKT and mTOR inhibitors in three breast cancer cell lines, MDA-MB-231, MCF7 and SK-BR3, which represent triple negative, ER-positive and HER2/Neu-positive breast cancers, respectively." (PMID 25857298, 2015). "Our data provides new mechanistic insight into the role of mTOR in the DNA damage response and support the clinical development of mTORC1/2 inhibitors in combination with DNA damage-based therapies for breast cancer." (PMID 25460505, 2015). "Measurement of p70S6K phosphorylation can potentially identify human breast cancers that would benefit from therapy with the mTOR allosteric inhibitor everolimus." (PMID 26148118, 2015). "Deregulations in downstream mTOR-related pathways diminish the effects of common adjuvant breast cancer treatments." (PMID 26698305, 2015). "In conclusion, this study revealed that patients weighted importance on PFS, anemia, and pneumonitis, when they needed to choose an aromatase inhibitor plus mTOR inhibitor for advanced breast cancer treatments after failure of standard treatments." (PMID 26558177, 2015).
breast cancer (continued). "The protein kinase mTOR is frequently activated in breast cancers, where it enhances cancer cell growth, survival, and metastastic spread to distant organs." (PMID 26132202, 2015). "First, metformin can decelerate the growth of hormone receptor-positive, HER2-positive breast cancer by suppressing the AKT/mTOR signaling pathway." (PMID 25935404, 2015). "IGF-2 expression is strongly enhanced in invasive breast cancers and downstream mTOR signaling is stimulated as is TNBC cell migration." (PMID 25874233, 2015). "It has been reported that overexpression of GOLPH3 promotes cell transformation by enhancing the activity of the serine/threonine kinase mTOR in breast cancer." (PMID 26375441, 2015). "CHD1L promoted the invasion and metastasis of breast cancer cells via the PI3K/Akt/ARK5/mTOR/MMP signaling pathway." (PMID 26599012, 2015). "IGF-2 expression is strongly enhanced in invasive breast cancers and stimulates downstream mTOR signaling and TNBC cell migration." (PMID 25874233, 2015). "miR-99a deregulation has been reported in several human cancers, including breast cancer, and is involved in apoptosis and epithelial-to-mesenchymal transition by regulation of the mTOR, Akt and TGF-β pathway." (PMID 26378051, 2015). "Everolimus, an allosteric mTOR inhibitor that inhibits the mTOR functional complex mTORC1, is approved for treatment of estrogen receptor positive (ER+) breast cancer." (PMID 26148118, 2015). "The BOLERO-2 trial was another randomised phase III trial in advanced breast cancer evaluating an mTOR inhibitor and aromatase inhibitor (AI) combination." (PMID 26779371, 2015). "This study highlights that acquisition of specific deregulated miRNAs is a newly discovered alternative mechanism developed by AI-resistant breast cancer cells to achieve constitutive activation of the AKT/mTOR pathway and to develop AI resistance." (PMID 25633049, 2015). "Among those pathways, the phosphatidylinositol 3-kinases (PI3 K)/Akt/mammalian target of rapamycin (mTOR) pathway plays an important role in breast cancer cell proliferation and cancer treatment resistance." (PMID 26558177, 2015). "The mTOR inhibitor everolimus has been beneficial in the treatment of advanced breast cancers resistant to endocrine therapies." (PMID 25849559, 2015). "Combined inhibition of PI3K/AKT/mTOR signalling with HER2/HER3 signalling inhibitors is therefore an attractive therapeutic strategy for the treatment of breast cancer." (PMID 26095475, 2015). "FAK signaling occurs in the nucleolus, active FAK protects NS, and Akt-mTOR pathway regulates NS protein stability needed for breast carcinoma spheroid and tumor growth." (PMID 25880415, 2015). "As rapamycin lowered NS levels in PTEN-mutated MDA-MB-468 breast carcinoma cells, our studies support a role for nucleolar-associated FAK signaling and Akt-mTOR activation in the maintenance of NS protein expression." (PMID 25880415, 2015). "In early stage, triple negative (estrogen and progesteron receptor, Her2 amplification) breast carcinomas, phosphorylated mTOR expression significantly correlated with worse overall survival and recurrence-free survival." (PMID 26097872, 2015). "Abnormal activation of PI3K/AKT/mTOR (PAM) pathway, caused by PIK3CA mutation, KRAS mutation, PTEN loss, or AKT1 mutation, is one of the most frequent signaling abnormalities in breast carcinoma." (PMID 25816324, 2015). "ZNF32 was shown to activate the AKT/mTOR pathway, which subsequently decreases the severe autophagic activity in breast carcinoma cells." (PMID 25786368, 2015). "The mTOR inhibitors rapamycin, everolimus, and temsirolimus are of particular interest for breast cancer bone metastasis because they have positive actions on bone in addition to sensitizing tumors to hormonal therapy and trastuzumab." (PMID 25757219, 2014). "Activation of the AKT/mTOR pathway is a poor prognostic factor for many types of cancers, including breast cancer." (PMID 24708766, 2014).
breast cancer (continued). "We have previously developed two hormone-resistant sub-lines of the MCF-7 human breast cancer line, designated TamC3 and TamR3, which were characterized by reduced mTOR signaling, reduced cell volume, and resistance to mTOR inhibition." (PMID 25232533, 2014). "Recently, clinical trials of combination chemotherapy and mTOR inhibitors in breast cancer demonstrated valuable results." (PMID 25115395, 2014). "Another potential limitation of this analysis is that a majority of our patients had breast cancer, and that the combination of an aromatase inhibitor and an mTOR inhibitor has recently been demonstrated to be effective." (PMID 24912489, 2014). "Since NF2 mutations activate mTor, we treated a patient with NF2-mutant metaplastic breast cancer (a highly refractory form of breast cancer) with a temsirolimus-based regimen, which resulted in a complete remission." (PMID 24393766, 2014). "It is well established that PI3K/Akt/mTOR pathway plays a central role in resistance to endocrine therapy in breast cancer, partly through regulation of estrogen receptor α (ER) activity." (PMID 25034939, 2014). "A link between the PI3K/mTOR pathway and AR signaling was previously established in prostate cancer and PIK3CA mutations are enriched in ER + breast cancer." (PMID 25103565, 2014). "In the last years the PI3K/AKT/mTOR signalling has been found to exert a central role in the regulation of breast cancer cell growth and to modulate oestrogen receptor function." (PMID 25338520, 2014). "PIK3CA mutations frequently occur in ERα-positive breast cancer and result in PI3K/AKT/mTOR activation in vitro." (PMID 24467828, 2014). "i.e., mTOR expression in these four breast cancer cell lines were markedly higher than that in breast epithelial cell line, and was associated with reduced miR-99a expression." (PMID 24637915, 2014). "Irradiation also induced phosphorylation of Akt and mTOR in a breast cancer cell line, which was attenuated by mTOR and PI3K inhibitors." (PMID 24989178, 2014). "We then compared mTOR and miR-99a expression in these tissues and found that among these 10 pairs of breast cancer tissues, there was a statistically significant inverse correlation between mTOR and miR-99a expression." (PMID 24637915, 2014). "This latter study suggests that in some breast cancers estrogen is regulating the activation of mTOR and removal of estrogen, through aromatase inhibition, decreased mTOR activation (at least as measured by decreased p-S2448-mTOR)." (PMID 24887419, 2014). "Six studies evaluated the expression of the PI3K/AKT/mTOR pathway in breast cancer, five in gastrointestinal tumors, three in gynecological cancers, and one each in prostate, non-small cell lung cancer (NSCLC) and oropharyngeal cancers." (PMID 24777052, 2014). "Animal studies confirmed that the combination of the FASN and mTOR inhibitors inhibited the progression of ER+/HER2+ breast cancer xenografts." (PMID 24866893, 2014). "Activation of the PI3K/AKT/mTOR pathway in breast cancer portends a worse prognosis, increased aggressiveness and resistance to treatment." (PMID 24684785, 2014). "In our study, we found that knockdown of mTOR expression using mTOR siRNA decreased breast cancer cell viability and induced apoptosis, a similar outcome to that of tumor cells transfected with miR-99a mimics." (PMID 24637915, 2014). "The cohort of breast cancer cases interrogated for mTOR and p-S2448 mTOR represented primary ERα + tumors from patients who received adjuvant tamoxifen therapy after surgery." (PMID 24887419, 2014). "Overexpression of miR-99a reduces breast cancer cell viability, induces apoptosis and inhibits tumorigenicity in vitro and in vivo through targeting mTOR/p-4E-BP1/p-S6K1 pathway." (PMID 24637915, 2014). "Overall, these results demonstrate 8-Cl-Ado treatment attenuated mTOR activity in breast cancer cells." (PMID 24628795, 2014).